EGFR (epidermal growth factor receptor)
Diseases named in the same sentence as EGFR in open-access papers (continued):
Sharing a sentence is not in itself a finding about the gene and the disease.
tumor (continued). "Prevention of spheroid formation by macrophage depletion or anti‐ICAM‐1 antibodies, or pharmacological blockade of EGFR, significantly delayed tumor growth, supporting that peritoneal macrophages are critical for ovarian cancer metastatic progression by driving spheroid formation." (PMID 36658699, 2023). "Notably, a study demonstrated that EGFR-CAR NK cells exhibited cytotoxicity and anti-tumor properties against TNBC cell lines with high EGFR expression." (PMID 37660039, 2023). "Thirty-nine (51%) patients received anti-EGFR-based therapy (16 patients panitumumab and 23 irinotecan plus cetuximab), 37 (49%) patients received R or T. Among patients with L-sided tumor, 30 (53%) were treated with anti-EGFR-based therapy and 27 (47%) with R/T." (PMID 36895480, 2023). "In the SINDAS study, which focuses on tumor harboring mutations in the epidermal growth factor receptor (EGFRm), LAT is also performed without upfront systemic therapy." (PMID 37958302, 2023). "Thus, Cy5-labeled dextraknobs comprising the anti-EGFR nanobody NBA as targeting protein showed a distribution in A431 tumor spheroids comparable to the nanobody directly labeled with a PS." (PMID 37896133, 2023). "Finally, in a subcutaneous tumor model, we showed that combining osimertinib with a PAI-1 inhibitor prevented the regrowth of tumors comprising EGFR-mutated cancer cells." (PMID 36831438, 2023). "Also, DS‐1205c restored antitumor activity of erlotinib in an erlotinib acquired‐resistance EGFR‐mutant NSCLC tumor xenograft mouse model." (PMID 36621830, 2023). "Few data are available about third-line anti-EGFR efficacy according to primary tumor site." (PMID 36895480, 2023). "Tumor-tumor interaction correlated with prolonged OS following EGFR TKI therapy (lower risk score; per 10%, HR = 0.73, 95% CI 0.58–0.90, P = 0.004), while tumor-stroma interaction negatively correlated with OS (higher risk score; per 10%, HR = 1.53, 95% CI 1.11–2.10, P = 0.009)." (PMID 36647832, 2023). "Combining ZLJT with EGFR-TKIs may alter signal transduction pathways, block the tumor cell cycle, inhibit tumor activity, enhance cellular vitality, and improve treatment effectiveness." (PMID 37990309, 2023). "Tumor biopsy of the present case at diagnosis was only tested for EGFR, ALK and PD-L1, resulted in negative driver gene mutation." (PMID 38134118, 2023). "Conversely, when the RTK/RAS pathway drives gliomagenesis (by NF1 inactivation and EGFR amplification in C3 and C4 models, respectively), the inferred tumor progression relies on the acquisition of PTEN alterations, and subsequent up-regulation of the PI3K pathway." (PMID 37770427, 2023). "In a dose-dependent manner, gefitinib could inhibit the growth of EGFR-overexpressing cell lines and human-derived tumor xenografts in mice." (PMID 38201251, 2023). "ALK and EGFR are extremely effective targets in the process of tumor therapy." (PMID 36903251, 2023). "This peptide also blocks cellular migration and survival in an EGFR- and tumor-specific manner." (PMID 36253541, 2023). "ZLJT may inhibit LUAD cell EGFR-TKIs resistance by altering signal transduction pathways, blocking the tumor cell cycle, suppressing tumor activity, enhancing cell vitality, and improving the bioavailability of coadministered drugs." (PMID 37990309, 2023). "Next, we established 3D organoids from one EGFR-mutant PDX tumour." (PMID 36810913, 2023). "Recent studies reveal that EGFR alterations not only promote GBM cell proliferation but also influence immune components in the tumor microenvironment (TME), leading to the recruitment of immunosuppressive cells (e.g., M2-like TAMs, MDSCs, and Tregs), and inhibition of T and NK cell activation." (PMID 37601668, 2023).
tumor (continued). "They found that EGFR ex20 ins-positive NSCLCs with high TMB, which is more common in smoking-associated cases, had a higher response rate to ICIs, potentially due to increased T-cell activity against neoantigens generated by tumor mutations." (PMID 37284196, 2023). "As an effector of oncogenic EGFR signalling, Fyn promotes tumour growth and motility." (PMID 38067326, 2023). "Further, ERBB2 mutations, NRG1 fusions, EGFR exon 20 insertions, NTRK rearrangements, and tumor molecular burden (TMB) could be promising targets in lung cancer and could be implemented in the test panels." (PMID 37445976, 2023). "The information that can be extracted from ctDNA could be used to confirm real-time tumor genetic information and to optimize the strategy of chemotherapy regimens, such as anti-EGFR mAb rechallenge and anti-EGFR mAb for NeoRAS WT mCRC." (PMID 36900264, 2023). "Who may benefit from the immunotherapy: PD-L1 TPS > 50%, smoking history, high tumor mutation burden, high CD8+ T cells, and/or specific subtypes of EGFR mutations?" (PMID 38001917, 2023). "In Meyer et.al, they identified balanced/wild-type EGFR expression within one clone and increased expression within another clone and its multiclonal parental culture, while the rest of the clones displayed EGFR amplification—in total six GSC cultures derived from within the same tumor." (PMID 38136371, 2023). "In tumor tissues, EGFR and HER2 expression levels were lower than that in the cell lines." (PMID 37798461, 2023). "Two patients with tumors harboring triple EGFR mutations of exon 19 del/T790M/C797S showed tumor shrinkage in both target and non-target lesions." (PMID 37296863, 2023). "hDT806 was engineered to target tumor-specific overexpressed EGFR and/or EGFRvIII mutants." (PMID 37898690, 2023). "After this filtering step, 38 out of 195 (19%) patients harboured activating EGFR mutations in healthy lung tissue that were not detectable in tumour tissue." (PMID 37020004, 2023). "Moreover, it was reported that a subset of tumors with anti-EGFR resistance also exhibited a pro-fibroblast phenotype and altered T cell infiltration in the tumor microenvironment." (PMID 37114077, 2023). "Although further study is needed, these data indicate that MCM4 may be a promising predictor for HER2/EGFR targeting UC and may promote tumor progression by participating in the EGFR/HER2 signaling pathways in UC." (PMID 37737200, 2023). "We found that, whereas in the 85–95% of the cases EGFR diploidy was associated with the CBX3 diploidy, the tumors displaying gene amplification of EGFR locus show a dramatic enrichment in the frequency of both low (gain; 10–90% of tumor specimens) and high (amplification; 5–80%) increase of CBX3 CN." (PMID 37633946, 2023). "For example, in patients, it has been demonstrated that a loading dose of 100 mg of unlabelled cetuximab or panitumumab saturates EGFR expression in normal tissue and, thus, optimizes tumor-to-background contrast subsequently obtained with fluorescently labelled cetuximab or panitumumab 49-51." (PMID 36593955, 2023). "Furthermore, the vascular endothelial growth factor (VEGF)/epidermal growth factor receptor (EGFR) signaling axis and the hypoxic tumor microenvironment are also implicated in macrophage recruitment in PDAC." (PMID 38099290, 2023). "MDA-MB-231 cells expressing EGFR were used as target tumor cells." (PMID 37349810, 2023). "Hence, it is likely that augmenting the expression level of JMJD5 in tumor cells through the uptake of exosomes, subsequently facilitating the degradation of intracellular EGFR, represents a novel tumor-suppressive mechanism of JMJD5." (PMID 37813845, 2023). "There is an important EGFR/CSF-1R paracrine loop between macrophages and tumour cells." (PMID 38143746, 2023). "Additionally, the tumor-promoting function of the activated EGFR in LIHC has been previously documented." (PMID 37229243, 2023).
tumor (continued). "These novel molecular markers might include EGFR and its downstream molecules or cellular markers affecting tumor stemness." (PMID 36891274, 2023). "Hence, determining the tumor's genotype has become crucial in planning treatment regimes in NSCLC patients, as the EGFR mutation status can predict the response to TKI drugs." (PMID 37425232, 2023). "Additionally, GEM is reported to suppress epidermal growth factor receptor (EGFR) by stimulating the expression of casitas B-lineage lymphoma (CBL) that promotes ubiquitination degradation of EGFR and inhibits tumor progression." (PMID 38174069, 2023). "Homology of RTK kinase domains and inhibition of Her3/4 and c-Met driven migration suggest cSNX1.3 could be effective in the inhibition of other RTKs that work with EGFR to drive tumor progression." (PMID 36253541, 2023). "We first used this workflow on tumor cell lines, including H1650, PANC-1, and HT-29, to assess whether the most common genetic mutations in EGFR (19del), KRAS (G12D), and BRAF (V600E)." (PMID 37849806, 2023). "EGFR was expressed by tumor cells as well, albeit generally at a much lower level than CAF." (PMID 37611111, 2023). "MYL1 facilitates tumor metastasis and correlates with tumor immune infiltration in HNSCC and these effects may be associated with the EGF/EGFR pathway." (PMID 37679666, 2023). "Therefore, early identification of patients with a high probability of tumor progression after EGFR-TKI therapy can facilitate the development of appropriate treatment strategies and is therefore crucial for the management of advanced NSCLC." (PMID 36670497, 2023). "Patients with untreated advanced (Stage IIIB–IV or relapsed) nonsquamous NSCLC without EGFR mutations according to single‐plex testing of tumor tissue, were enrolled into this study." (PMID 37948122, 2023). "Also, the EGFR mutation, one of the most common mutations in NSCLC, found in pathological assessment of tumor HROLu22, is present in the WES (raw) data but was discarded in the final report for not passing the variant call quality control filter." (PMID 37228492, 2023). "When SERS gold nanoparticles were injected through the tail vein of mice, the nanoparticles were targeted to bind to EGFR positive tumor cells and located in intracellular organelles, such as endosomes and lysosomes, while accumulation was hardly observed in the brain, muscle, or other major organs." (PMID 37149605, 2023). "In addition, we for the first time, demonstrate that ADAM12 can further induce EMT and promote tumor progression in ccRCC through the EGFR/ERK signaling pathway." (PMID 36717944, 2023). "Among these patients, nine had a smoking history, whereas only one, whose tumor harbored an EGFR mutation, had no smoking history." (PMID 38203395, 2023). "EGFR is an antigen expressed in both epithelial cancers and healthy epithelial cells; thus, its targeting has raised many concerns as regards on-target off-tumor toxicities." (PMID 37646900, 2023). "Furthermore, tumor location is known to be associated with differences in key tumorigenic molecular features, including microsatellite instability (MSI) and epidermal growth factor receptor (EGFR)." (PMID 36802389, 2023). "Neoadjuvant or perioperative chemotherapy plus an ICI would now be the preferred approach for resectable stage III NSCLC for the majority of patients unless they have tumours with molecular abnormalities, such as EGFR or ALK, or have contraindications to the use of an ICI." (PMID 37999109, 2023). "In this light, dual inhibition of EGFR activation and PGE2 production may be a strategy to inhibit tumor progression and overcome EGFR therapy resistance." (PMID 37190301, 2023). "Based on the preliminary anti-tumor mechanism experimental results, 5i is a promising leading compound that can induce autophagy by promoting EGFR recycling and signal transduction, and therefore, it can provide a new research path for the development of effective autophagy inhibitors." (PMID 37110525, 2023).
tumor (continued). "EGFR is known to be highly expressed on various cancer cells, and the level of expression can directly correlate with the stage of a cancerous tumor; that is why it is a key target in the delivery of drugs to organs affected by a cancerous tumor." (PMID 36834993, 2023). "For instance, in a study focusing on Treg cells in HCC, it was observed that the expression level of long noncoding RNA lnc-EGFR (Epidermal Growth Factor Receptor) was elevated, showing a positive correlation with tumor size and EGFR/forkhead box protein 3 (Foxp3) expression levels." (PMID 37609076, 2023). "Our study also demonstrates a potential of TMEM25 for targeted therapy of TNBC, and suggests that clinical mutations of TMEM25 identified in other types of cancer may be able to trigger monomeric-EGFR/STAT3 signaling to promote tumor progression as well." (PMID 37095176, 2023). "Accordingly, EGFR targeted therapies in these tumor types may be beneficial in treatment of MIBC basal subtype." (PMID 36737799, 2023). "The information on the staging, histology, and blood analysis results of NSCLCs patients could be used to provide a reliable prediction of possible tumor progression after EGFR-TKI treatment." (PMID 36670497, 2023). "The expression of betacellulin, which belongs to the EGF family, in HCC cells has been shown to have a significant positive correlation to EGFR expression by tumor endothelial cells, suggesting a potential paracrine signaling pathway to induce tumor angiogenesis." (PMID 38173713, 2023). "Indeed, in our cohort we clearly defined EGFR membrane expression and found that about 50% of the OCs express EGFR on tumor cell membrane and 4,2% of them showed high and homogeneous EGFR membrane expression." (PMID 37041632, 2023). "Tumor response of first-line EGFR-TKI or chemotherapy in patients." (PMID 37503313, 2023). "Moreover, IHC assay using xenograft OSCC tumor showed that FMOD knockdown inhibited OSCC progression through suppressing EGFR/AKT or EGFR/ERK signaling axis." (PMID 37965134, 2023). "Most BA/CMPT cases have been reported from Japan and other Asian countries and may involve genetic mutations of BRAF, EGFR, KRAS, HRAS, and ALK; thus, the tumor is viewed as an oncological disease." (PMID 39517003, 2023). "To examine whether a monovalent anti-TAA Fab was sufficient for targeting high density receptors on tumor cells, we generated anti-EGFR (clone GA201)/anti-CD3 (clone UCHT1) TED (hereafter EGFR TED) to test its cytotoxicity against the OVCAR3 cell line." (PMID 38022650, 2023). "Four patients (D045, D989, D270, and D372) with documented EGFR mutations in tumor tissue carried no detectable EGFR mutations in the corresponding plasma samples using both cfDNA assays." (PMID 37372399, 2023). "Accordingly, prior intense treatment history might have a significant effect on the tumor genome, thereby boosting the shift in genomic landscape of tumors with EGFR dominancy, as shown in our study." (PMID 37537946, 2023). "In recent years, studies showed neoadjuvant EGFR-TKI therapy could downstage the tumor and improve the rate of radical surgery in patients with locally advanced NSCLC." (PMID 36776292, 2023). "EGFR is expressed in normal cells but overexpressed in tumor cells." (PMID 36707873, 2023). "The concordance rate of EGFR between primary tumor and metastasis can range from 100% to 72%." (PMID 37345046, 2023). "However, the epidermal growth factor receptor (EGFR) related to tumor invasion and metastasis was expressed less in the FerrLowImmHigh group." (PMID 36671532, 2023). "Moreover, NSCLC patients with uncommon EGFR mutation, including G719X, L861Q, S768I, and Ex20 ins, had more abundant PD-L1 expression accompanied by CD8+ tumor-infiltrating lymphocytes(TILs) infiltration." (PMID 37090727, 2023). "A monovalent EGFR-targeted nanobody and biparatopic version modified with different dextran average molecular weights (1000, 5000, and 10,000) were probed for their ability to penetrate tumor spheroids." (PMID 37896133, 2023).
tumor (continued). "In addition, it has been shown that Sortilin is a key element in the biogenesis of exosomes expressing TrkB and EGFR, which appears to favor angiogenesis within the tumor microenvironment." (PMID 37576898, 2023). "The results showed that the EGFR was successfully expressed on the surface of the T7 phage, and thus the recombinant phage could effectively inhibit tumor growth in the BALB/c mouse model." (PMID 37809683, 2023). "CEA level was correlated with the mutation detection rate of EGFR in plasma (r = 0.39, p < 0.05), and no more associations of driver gene mutations with serum tumor markers were observed." (PMID 36341686, 2023). "The up-regulation of genes of the EGFR_EMT_Signature in patients may reflect a high degree of EGFR-EMT along with increased tumor cell dissemination and thus a benefit to treat patients with Cetuximab." (PMID 37620936, 2023). "EGFR tyrosine kinase inhibitors (TKIs) have been used as adjuvant therapy after tumor resection as multiple randomized trials have demonstrated their effectiveness, as first‐line treatment for EGFR exon 19 deletions or exon 21 L858R mutations of NSCLC patients." (PMID 38090373, 2023). "Additionally, Western blot analysis of tumor tissues demonstrated that theasinensin A plus nimotuzumab resulted in a greater suppression of p-EGFR, p-ERK1/2, p-STAT3 and p-GSK3β." (PMID 37762316, 2023). "EGFR is also a key driver of tumor progression and drug resistance in many cancers." (PMID 37160944, 2023). "The scFv-TMs could induce the lysis of tumor cells with low EGFR expression levels more efficiently than the Nb-TMs, which may increase the risk of targeting healthy tissues." (PMID 36761751, 2023). "Finally, an overview of liquid biopsy approaches involving EGFR and EVs in the blood/plasma of EGFR-dependent tumour patients will also be discussed to evaluate their possible application as candidate biomarkers." (PMID 37296932, 2023). "The ability of this enzyme to negatively regulate several receptor-type PTKs related to oncogenesis, including the epidermal growth factor receptor (EGFR) and IR, suggested that it could act as a tumor suppressor." (PMID 37298571, 2023). "The tumor cell line EGFR expression was determined using quantitative flow cytometry (Section S5)." (PMID 34651290, 2023). "The tumor pathways of Epithelial cells are mainly enriched in EGFR and MAPK, and the significant enrichment of these two ‘star pathways’ may suggest a significant role of Epithelial cells in the development of ESCC." (PMID 37025404, 2023). "Despite E-cadherin expression in IHC stain, cleaved E-cadherin fragments (soluble E-cadherin) may have an oncogenic effect, increase tumor cell motility and survival, and play a role in EGFR and Wnt/β-catenin pathway signaling." (PMID 37340370, 2023). "EGF and EGFR increase tumor cell viability, migration and invasion by PI3K/AKT and MEK/ERK pathway." (PMID 37679666, 2023). "EGFR transcripts in the primary tumor were also confirmed by using RT-PCR." (PMID 36675253, 2023). "Oncogenes on these chromosomes gain extra copy number may promote tumor proliferation, such as EGFR on chromosome 7 and ERBB2 on chromosome 17." (PMID 37784106, 2023). "• The intrinsic tumor heterogeneity can be highly dynamic under the therapeutic effect of EGFR-TKI treatment, and the inevitable development of drug resistance may disrupt the duration of clinical benefit." (PMID 36166088, 2023). "Notably, in a specific clinical trial (NCT01869166), on-target/off-tumor toxicity occurred with anti-EGFR CAR-T cell therapies, as EGFR is present in most normal epithelial cells." (PMID 36564524, 2023).